ZFTRAF1 (zinc finger TRAF-type and ring finger containing 1)
Synonyms: CYHR1; KIAA0496; CHRP; MGC13010
Tractability: No criterion of Open Targets' tractability assessment is met for any kind of drug.
Gene: Protein-coding gene on chromosome 8 (144,449,582 to 144,462,871, reverse strand). Ensembl gene ENSG00000187954.
Subcellular location: Cytoplasm; Cytoplasm, perinuclear region
Subcellular location (Human Protein Atlas): Nucleoplasm
Gene Ontology:
Molecular function: protein binding; zinc ion binding
Cellular component: cytoplasm; perinuclear region of cytoplasm
Genetic constraint (gnomAD): Loss-of-function variants: 9 observed, 13.5 expected, observed/expected ratio (o/e) 0.67, 90% interval 0.4 to 1.16. The upper end of that interval is the gene's LOEUF score, 1.16, which puts it in group 5 of 6, group 1 being the genes least tolerant of losing a copy. Missense variants: 118 observed, 203.48 expected, observed/expected ratio (o/e) 0.58, 90% interval 0.5 to 0.68. Synonymous variants: 98 observed, 77.9 expected, observed/expected ratio (o/e) 1.26, 90% interval 1.07 to 1.49.
Homologues: Orthologues: chimpanzee CYHR1 (100% identical), macaque CYHR1 (99% identical), dog CYHR1 (98% identical), pig ZFTRAF1 (97% identical), rat Tmem276-zftraf1 (97% identical), chimpanzee CYHR1 (95% identical), zebrafish zftraf1 (74% identical), rabbit TMEM276-ZFTRAF1 (71% identical), guinea pig ZFTRAF1 (70% identical), mouse Gm57852 (70% identical), Drosophila melanogaster CG32486 (45% identical).
Diseases named in the same sentence as ZFTRAF1 in open-access papers:
ZFTRAF1 is named in the same sentence as 5 diseases in open-access papers, as found by Europe PMC text mining. Sharing a sentence is not in itself a finding about the gene and the disease.
ZFTRAF1 shares sentences with these, for which no sentence is quoted: cancer (1 paper); cervical cancer (1); esophageal squamous cell carcinoma (1); glioma (1); lymphoma (1).